CRP (C-reactive protein)
Diseases named in the same sentence as CRP in open-access papers (continued):
Sharing a sentence is not in itself a finding about the gene and the disease.
infection (continued). "At the time of PJI diagnosis, patients with an unresolved infection had a significantly higher mean C-reactive protein (CRP) value (1.7-fold) than those whose infection was resolved." (PMID 35762769, 2022). "The suspicion appeared strengthened when MAP was combined with lower infection index including the white blood cell count, percentage of neutrophils and serum CRP." (PMID 36109705, 2022). "CRP values require 10-12 hours to change after the onset of infection, has a half-life of 24-48 hours, and is measured on a regular basis to decide the length of antibiotic treatment." (PMID 35449688, 2022). "Key areas of the inflammatory response to CRP-mediated infections include the complement pathway, apoptosis, phagocytosis, NO release, and pro-inflammatory cytokine production, particularly IL-6 and TNFα." (PMID 35453906, 2022). "CRP is an acute inflammatory protein, which values increase during infections, damage of tissue and also during autoimmune diseases." (PMID 36431053, 2022). "According to previous studies, CRP appears to be a more sensitive and specific marker of postoperative infections than ESR and white cell count." (PMID 35991254, 2022). "This study aims to evaluate the potential of C-reactive protein to lymphocyte count ratio (CLR) for the prediction of surgical site infection (SSI) following posterior lumbar interbody fusion (PLIF) and the instrumentation of lumbar degenerative diseases." (PMID 36268214, 2022). "In our study, CRP at a cut-off value of 5.3 mg/dL had a sensitivity of 54.9% and specificity of 69.6% in the diagnosis of infection." (PMID 36143057, 2022). "When patients were divided according to the level of CRP, it was worth noting that patients with elevated CRP had an additional chance of developing serious infections after receiving Tocilizumab (47.8% versus 11.8%, p=0.0204)." (PMID 35799791, 2022). "It is possible that this finding resulted from failure to diagnose infection due to supressed inflammatory responses, most especially C-reactive protein and procalcitonin concentrations." (PMID 35922860, 2022). "In our study, patients with a definitive infection showed significantly higher serum CRP levels compared to patients with probable or possible infections." (PMID 33515325, 2022). "Ninety-nine children (36.7%) in the HBoV single infection group displayed elevated CRP levels, compared with 26 children (24.8%) in the hMPV group (χ2 = 4.821, P = 0.038)." (PMID 36704137, 2022). "Regression of serological infection indicators [such as interleukin-6 (IL-6), C-reactive protein (CRP), white blood cell count (WBC)] to the normal range was regarded as one of the diagnostic tests with high sensitivity to radical debridement." (PMID 36299571, 2022). "The hepatic synthesis rate of CRP increases within hours after the onset of infection and can increase up to 1000-fold from baseline levels." (PMID 36517750, 2022). "CRP sensitivity is lowest during the early stages of infection and increases dramatically within 24–48 hours after the onset of symptoms." (PMID 36517750, 2022). "The validity results showed that those with infection were older and had a greater median CRP; WCC and ALT." (PMID 35778707, 2022). "Higher levels of CRP during COVID-19 infection have been used as an indicator of disease severity, as they indicate a severe infection course." (PMID 36431053, 2022). "CRP is produced in the liver and responds to infections and inflammations due to the release of cytokines such as interleukin-1 (IL-1), interleukin-6 (IL-6), and tumor necrosis factor alpha (TNF-α)." (PMID 36291945, 2022). "Among these, acute decompensation was triggered by infection in 1,102 (19.6%) patients and these patients exhibited higher CRP levels than their counterparts (4.23 ± 6.02 mg/dL vs. 1.88 ± 3.52 mg/dL, P < 0.001)." (PMID 36620625, 2022).
infection (continued). "In particular, laboratory parameters of infection such as C-reactive protein (CRP), procalcitonin (PCT) and interleukin 6 (IL-6) are able to provide valuable information on the presence and progression of infection." (PMID 35887994, 2022). "In order to compare this new generation biomarker with the current parameter used in the clinical practice, this longitudinal study evaluated C reactive protein as the main inflammatory marker used in the clinical evaluation of patients displaying infections." (PMID 35740951, 2022). "The infection parameters (white blood cell count, erythrocyte sedimentation, and C-reactive protein) were all within normal limits." (PMID 36232194, 2022). "Only 7.2% of the pregnant women had acute inflammations/infections judged by serum CRP > 10.0 mg/L and only 1.6% of the women had chronic inflammations/infections judged by serum AGP > 1.0 g/L." (PMID 33572898, 2021). "Infection parameters C-reactive protein (CRP) and CSF leukocyte count decreased within 7 days after initiation of antibiotic therapy in all patients." (PMID 34827359, 2021). "Mean serum C-reactive protein and procalcitonin concentrations were also higher in infection cases; white blood cell count, however, was decreased in some infection cases." (PMID 34513755, 2021). "In fact, CRP usually peaks within 36–50 h from the infection onset and falls to normal within a week of successful treatment, so it can be used also for monitoring the course of the disease." (PMID 34682177, 2021). "This study found that the retinal venular calibre in hospitalized patients with infections and CRP levels > 100 mg/L decreased when the follow-up CRP was < 100 mg/L after antibiotic treatment." (PMID 34446820, 2021). "As a proinflammatory cytokine, IL-6 was available in peripheral blood at the early stage of the infection, which then led to the generation of CRP in the liver." (PMID 33575324, 2021). "CRP is an acute-phase protein generated by hepatocytes in response to infection, inflammation, or tissue damage-induced cytokines from leukocytes." (PMID 34573923, 2021). "Although the number of infections with a detected microorganism was small in our study (n = 46), we observed a significantly lower serum CRP level in the low-virulence group (p = 0.044), which is in line with the currently available literature." (PMID 33247312, 2021). "While the decline in laboratory infection surrogates (C-reactive protein [CRP] and procalcitonin [PCT]), APACHE II score and vasopressor dependence (VIS) did not significantly differ between both groups." (PMID 34201244, 2021). "CRP is a major acute phase reactant in humans, with an acute and rapid rise in response to infection and tissue damage." (PMID 34356979, 2021). "PCT has a half-life of 22-29 h and the secretion in bacterial infections starts to rise 4 h after the onset of infection, peaking at 12–24 h, earlier than CRP which peaks at 2–3 days with a half-life of 12–24 h." (PMID 33708198, 2021). "CRP had the best accuracy with an area under the ROC curve (AUC) of 0.79 (95%-CI 0.66–0.92) to diagnose confirmed infection and an AUC of 0.72 (0.61–0.84) to diagnose confirmed and suspected infection." (PMID 35155322, 2021). "Rapid hepatic synthesis of CRP occurs as part of the acute phase response to infection, injury or trauma." (PMID 33628645, 2021). "As shown in our study, despite there was some correlation with SpO2, a ratio of PaO2/FiO2, or with CRP, the IL-6 level varies significantly during the infection and has independent meaning, which leaves space to optimizing patient selection." (PMID 33679753, 2021). "When PCT and CRP are used in combination, they can make up for each other’s shortcomings, improve the specificity and sensitivity of infection diagnosis, and allow early treatment decisions for clinicians." (PMID 34233608, 2021). "Elevated CRP was reported as a predictor of postoperative surgical site infection, postoperative infection, and general complication rate." (PMID 33902505, 2021).
infection (continued). "C-reactive protein (CRP) is an acute-phase protein in humans that is produced in high quantities by the liver upon infection and under inflammatory conditions." (PMID 34769069, 2021). "But currently, there are no recognized standard biomarkers to assess SCI levels alone, and SCI is typically measured by combining biomarkers of acute inflammation and infection, e.g., CRP, IL-6, and TNFα." (PMID 34925360, 2021). "In the present study, 37 (7.2%) pregnant women had acute inflammation/infection judged by serum CRP concentration > 10.0 mg/L, and 8 (1.6%) pregnant women had chronic inflammation/infection judged by serum AGP concentration > 1.0 g/L." (PMID 33572898, 2021). "CRP is an acute-phase protein produced by the liver, which is a common biomarker for the diagnosis of infection and inflammation in clinical treatment." (PMID 34281552, 2021). "The average CRP concentration in B. canis single infection was higher than E. canis and H. canis single infections." (PMID 34566333, 2021). "Infection biomarker the CRP level decreased significantly, with still slightly more than 10% increased CRP level." (PMID 33983981, 2021). "CRP is an acute phase reactive protein that is induced by interleukin-6 under stress states, including infection and synthesis by the liver." (PMID 34290800, 2021). "Among 68 patients who had normal CRP levels, body temperature, and white blood cell counts, 94% had signs or symptoms of infection." (PMID 33804790, 2021). "The availability of unpublished results allowed us to examine the effects of a number of important confounding factors, including suspected infection (CRP > 10 mg/L) at baseline (time of blood sampling)." (PMID 34050185, 2021). "For example, CRP is one of the strongest markers of the innate immune system, and is considered a clinically and pathologically significant acute-phase marker of infection and inflammation." (PMID 33514832, 2021). "The infection status was adjudicated using chart review (including a syndromic molecular respiratory panel, procalcitonin and C-reactive protein) by three infectious disease physicians blinded to InSep results." (PMID 34142256, 2021). "A key marker for parainflammation in the periphery is a smoldering, subtle 50–75% elevation in the level of acute phase proteins such as CRP, in contrast to CRP responses to infection that rise quickly 100-fold or more." (PMID 34502154, 2021). "IL-6 and CRP as acute phase reactants are elevated in response to infection, with IL-6 as the main inducer of CRP expression." (PMID 34680581, 2021). "C-reactive protein (CRP), an acute-phase protein released by macrophages, remains the most frequently used biomarker for both infection and inflammation diagnosis in clinical practice." (PMID 34281552, 2021). "C-reactive protein, a well-known marker for detecting both local and systemic inflammation and infection, has been frequently used in daily clinical practice." (PMID 34830626, 2021). "Patients with persistent infection had a significantly higher C-reactive protein on admission (49.4 vs. 14.3 mg/L, p = 0.003) and mortality (6/11 vs. 6/38, p = 0.02), compared to patients with successful eradication of infection." (PMID 34768706, 2021). "C-reactive protein (CRP) is a positive acute-phase reactant used for the diagnosis and evaluation of therapeutic efficacy in patients with infection/inflammation." (PMID 35008742, 2021). "This was further subjected to multivariate analysis which showed infection and high CRP levels were related to a poorer prognosis." (PMID 34804679, 2021). "The concentration of CRP in plasma increases greatly during the acute phase response to tissue injury, infection, or other inflammatory stimuli." (PMID 33952343, 2021). "C-Reactive Protein (CRP) is an acute-phase protein biomarker that is generated in response to acute injury, infection or other inflammatory stimuli." (PMID 34209146, 2021).
infection (continued). "The use of the maximum CRP level as an index allows, for example, an infection assessment and preliminary discussion of the timing of CT re‐imaging and drainage." (PMID 34386599, 2021). "Levels of markers such as Serum Amyloid A and Neutrophil CD64 increase more rapidly post-onset of infection compared to CRP." (PMID 34522543, 2021). "SAA is a robust, clinically utilized acute phase reactant which is arguably as or more sensitive for infection and inflammation as the C-reactive protein, and plays active roles in innate immunity." (PMID 33897686, 2021). "We show that both GoF C2 variants increase the deposition of C3 in the presence of C-reactive protein (CRP), an acute phase protein that elevates its concentration in plasma up to 1,000 times upon infection and/or inflammation." (PMID 34899688, 2021). "Although serum CRP has been suggested as a biomarker of infection in acute exacerbations of COPD, evidence has shown that antibiotic therapy is guided by procalcitonin levels, a systemic marker of bacterial infection, which safely reduces antibiotic use." (PMID 34587911, 2021). "A prospective evaluation Use of erythrocyte sedimentation rate and C-reactive protein level to diagnose infection before revision total knee arthroplasty." (PMID 32666142, 2021). "C-reactive protein (CRP) is a well characterized inflammatory marker widely used to help in the diagnosis of infection." (PMID 33879189, 2021). "We then explored the relationship of preinfection neutrophils and CRP with infection outcome in our cohort in more detail." (PMID 34121360, 2021). "IL-6 is a pleiotropic cytokine that is known to induce release of CRP in response to inflammation or infection." (PMID 34630395, 2021). "Elevated serum C-reactive protein, a protein whose expression is driven by IL-6, is also a biomarker of severe infection." (PMID 33917093, 2021). "Other risk factors for CRS include the administered dose of therapy, circulating disease and the presence of a pre-existent state of inflammation with either active infection, high ferritin or high C-reactive protein (CRP)." (PMID 33946635, 2021). "Clinical infection index including the C-reactive protein (CRP) and erythrocyte sedimentation rate (ESR) was also reviewed." (PMID 33542353, 2021). "This dynamic aspect has been observed for CRP on a longer period mainly in the context of infection." (PMID 33708198, 2021). "An explanation is that CRP is an unreliable marker of infection in patients on surgical ICUs as CRP levels can vary as a consequence of surgical trauma or liver insufficiency." (PMID 34201244, 2021). "During inflammatory disease phases of infection, CRP can activate the immune system classical complement cascade and modulate phagocytic cell activity." (PMID 33854695, 2021). "CRP is an innate acute phase protein produced by the liver and has been used as a systematic marker of tissue injury, infection, and inflammation in clinics." (PMID 34900028, 2021). "These tests that are currently recommended by most of the infection societies include serum CRP and ESR, synovial fluid CC and PMN%, synovial fluid extended cultures, and should be done for every case when PJI is suspected." (PMID 33619607, 2021). "In future studies, these will be compared with CRP values and other traditional methods of infection detection prospectively." (PMID 34768504, 2021). "We also analyzed G-CSF (a BAFF-promoting cytokine, also central for emergency neutropoiesis) and C-reactive protein (CRP, as a sign of inflammation/infection)." (PMID 34003398, 2021). "CRP is used to assess inflammation in the body, and its role in combating infection has been determined." (PMID 35096716, 2021). "CRP is a protein that increases synthesis in the liver against infection, inflammation, or tissue damage in our body." (PMID 34362075, 2021).
infection (continued). "With multivariate linear regression, BLR reached an adjusted R2 of 0.46, indicating that 46% of the variance in BLR can be explained by age, CRP, focus of infection, type of bacteria, and glucose level before FDG-PET/CT." (PMID 33106925, 2021). "The role of the classical pathway has been investigated through the manipulation of C-reactive protein (CRP), an inflammatory protein that significantly increases at the sites of inflammation during infection." (PMID 34757496, 2021). "The course of infection was monitored by means of laboratory parameters such as leukocyte counts and c-reactive protein levels." (PMID 33532496, 2021). "The C-reactive protein (CRP) levels in patients with mild and severe infection were also studied to develop a predictive marker." (PMID 34975833, 2021). "By using the t-test, there were statistically significant differences for mean values of PCT, PSPN and CRP between the two groups, and this difference was in favor of the patient group with infection." (PMID 34324506, 2021). "Hospital inpatients with severe infections had retinal venular calibre that decreased as their infections resolved and CRP levels fell after antibiotic treatment." (PMID 34446820, 2021). "We conducted this study to report cases treated with tocilizumab who developed serious infections with special reference to levels of CRP and to review the literature on the effect of tocilizumab on acute phase response (APR) during infections." (PMID 33804790, 2021). "The objective of this study was to review nine patients treated with TCZ who were hospitalized at our center due to serious infections, and place special emphasis on the CRP status during the severe infectious event that required the index hospitalization." (PMID 33804790, 2021). "Compared with survivors, deceased patients had higher levels of infection-related biomarkers, such as CRP (104.8 vs. 33.7 ng/mL; P < 0.001), and ferritin (2022.5 vs. 610.9 ng/mL; P < 0.001)." (PMID 33664741, 2021). "C-reactive protein (CRP) is an inflammation biomarker that should be quantified accurately during infections and healing processes." (PMID 34940253, 2021). "It has a half-life of 21 h in neonates, and it takes 10–12 h for CRP to change significantly after onset of infection." (PMID 33673378, 2021). "Levels of infection-related indices, such as interleukin 6 (IL-6) (35 (24.10%)), C reactive protein (CRP) (40 (19.00%)) and ESR (19 (17.00%)), were also elevated in some patients." (PMID 34697118, 2021). "CRP is an acute phase inflammatory marker of systemic inflammation that is mainly produced by hepatocytes in response to infection, liver injury or inflammatory cytokine release." (PMID 35070979, 2021). "For SLR, age, CRP, focus of infection, and glucose before FDG-PET/CT reached an adjusted R2 of 0.19." (PMID 33106925, 2021). "CRP mediated 66% of the association of CAD+AMI− with all-cause mortality (P = 0.048) and 73% of the association with infection-related mortality (P = 0.035)." (PMID 34315941, 2021). "Interpretation of other biomarkers of infection such as C-reactive protein (CRP) and WCC can also vary with the mode of delivery that women experience." (PMID 34301187, 2021). "Infection-related inflammatory indexes, such as c-reactive protein (CRP), white blood cells (WBC), and neutrophils were completely improved 1 week after surgery." (PMID 34332562, 2021). "There was a significant difference between the PSI group and the non-infection group for CRP (p = 0.004) and ESR (p = 0.002)." (PMID 35011791, 2021). "CRP and full blood examinations are already routine blood immunoassays utilised in the diagnosis of infection and therefore have known parameters and remains stable when affected by delays into processing." (PMID 33794783, 2021). "The physician judged that his infection was getting past the acute stage as the CRP level was mildly elevated; however, the WBC and other data were within normal limits." (PMID 34468333, 2021).